CD40 (CD40 molecule)
Diseases named in the same sentence as CD40 in open-access papers (continued):
Sharing a sentence is not in itself a finding about the gene and the disease.
inflammatory bowel disease (20 papers, 2010 to 2025). A spectrum of small and large bowel inflammatory diseases of unknown etiology. "Then, we aimed at addressing the influence of the functional polymorphism at −1 of the CD40 gene in inflammatory bowel disease risk." (PMID 20634952, 2010). "We hypothesized that this functional polymorphism might also show an association with other complex autoimmune condition such as inflammatory bowel disease, given the CD40 overexpression previously observed in Crohn's disease (CD) lesions." (PMID 20634952, 2010). "Thus, we decided to focus attention on this component of the CD40/CD40-ligand costimulatory pathway and to investigate the association of the functional polymorphism of the CD40 gene in the two main clinical phenotypes of inflammatory bowel disease, Crohn's disease (CD) and ulcerative colitis (UC)." (PMID 20634952, 2010). "In conclusion, our findings suggest that MLT mitigates inflammation in cIECs by modulating the transcription of ZAP70 and CD40 through histone modifications, offering potential therapeutic insights for inflammatory bowel diseases." (PMID 40005847, 2025). "Generalised disruption of the CD40–CD154 pathway was attempted in clinical trials of individuals with lupus nephritis and inflammatory bowel disease (CD40-driven diseases) using neutralising monoclonal antibody (mAb) against CD154." (PMID 35920844, 2022). "Furthermore, during active inflammatory bowel disease (IBD), intestinal epithelial cells (IECs) express CD40, indicating that CD40 has a role in stimulating proinflammatory responses." (PMID 40005847, 2025). "In inflammatory bowel disease, activated DCs could release the inflammatory cytokines such as IL-6, IL-12 and tumor necrosis factor (TNF-α) by up-regulating the pattern recognition receptors [Toll-like receptor (TLR) 2 and TLR4], MHC class II molecules, and costimulatory molecules (CD40 and CD86)." (PMID 37670381, 2023). "The DC surface receptor costimulatory molecules CD86, CD80, CD83, and CD40 generate important signals for stimulating naive T cell differentiation and may inhibit oral tolerance in not only IDDM but also inflammatory bowel disease (IBD) and multiple sclerosis." (PMID 28396662, 2017).
chronic lymphocytic leukemia (19 papers, 2010 to 2026). "In leukemias, MiR-29a deficiency activates CD40 signaling/T-cell interaction to engage in chronic lymphocytic leukemia pathogenesis; meanwhile, it is greatly dysregulated in acute myeloid leukemia, chronic lymphocytic leukemia, and ALL patients." (PMID 35311115, 2022). "Tumor necrosis factor (TRAF4), which is connected to CD40 activation and B-cell receptor signaling, is affected by miR-29, which is observed in chronic lymphocytic leukemia (CLL)." (PMID 41614928, 2026). "In CD40-expressing malignancies, such as chronic lymphocytic leukemia, CD40 monoclonal antibodies (mAbs) mediate direct tumor cell death via antibody-dependent cellular cytotoxicity." (PMID 33572196, 2021). "Lumiliximab is a Mab able to bind CD23, a low-affinity IgE receptor found to be higly expressed on chronic lymphocytic leukemia (CLL) cells, whereas dacetuzumab (also known as SNG-40) targets CD40, a molecule expressed on several types of B cells neoplasms." (PMID 31799195, 2019). "For instance, activating antibodies to CD40 (CD40 mAb) or soluble CD40L possess therapeutic potential, for example in the treatment of lymphoproliferative malignancies such as non-Hodgkin lymphoma, chronic lymphocytic leukemia, diffuse large B-cell lymphoma and advanced solid tumors." (PMID 34440067, 2021).
pancreatic ductal adenocarcinoma (19 papers, 2010 to 2026). An infiltrating adenocarcinoma that arises from the epithelial cells of the pancreas. "It was reported that CD40 agonists can mediate tumor regression in pancreatic ductal adenocarcinoma in mice and patients, in which the underlying immune mechanism can be both T-cell-dependent and T-cell-independent." (PMID 37024802, 2023). "Surprisingly, it was observed that patients with pancreatic ductal adenocarcinoma (PDAC) who had low exo-CD40 expression had a longer survival rate compared to those with high exo-CD40 expression." (PMID 40003965, 2025). "Agonistic anti-CD40 monoclonal antibody (mAb) therapy in combination with chemotherapy (chemoimmunotherapy) shows promise for the treatment of pancreatic ductal adenocarcinoma (PDA)." (PMID 33497362, 2021). "The combination of MEK inhibition with agonist anti-CD40 Ab is therefore a promising therapeutic concept, especially for the treatment of mutant Kras-driven tumors such as pancreatic ductal adenocarcinoma." (PMID 32358491, 2020). "For example, miR-224 is up-regulated in highly invasion pancreatic ductal adenocarcinoma, and it is correlated with the down-regulation of CD40, which it is predicted to target." (PMID 20354523, 2010). "To do this, we analyzed serum aspartate aminotransferase (AST) and alanine aminotransferase (ALT) levels collected on patients with pancreatic ductal adenocarcinoma (PDAC) treated on a clinical trial with the fully human agonist CD40 antibody CP-870,893 in combination with gemcitabine chemotherapy." (PMID 34101617, 2021). "The utilization of a mAb anti-CD40, CP-870893, targets the non-ligand binding site of CD40, enhance the secretion of IL-12, IL-23, and IL-8 and in combination with gemcitabine, is associated with antitumor activity in pancreatic ductal carcinoma patients." (PMID 35011682, 2021). "The latest preclinical data on pancreatic ductal adenocarcinoma indicate that the combination of anti-TNFR2 and CD40 agonists demonstrates superior efficacy compared to monotherapy by eliminating activated Treg cells and alleviating CD8 depletion." (PMID 41438755, 2025). "In pancreatic ductal adenocarcinoma (PDAC), CD40 agonists have demonstrated the ability to reprogram tumor-associated macrophages (TAMs) into tumoricidal cells that facilitate stromal remodeling and promote T cell–independent tumor regression." (PMID 40821795, 2025). "In the case of pancreatic ductal adenocarcinoma (PDAC), which often exerts immunosuppressive effects, targeting CD40 has shown potential in altering the immune microenvironment of tumors." (PMID 40003965, 2025). "In pancreatic ductal adenocarcinoma (PDAC), CD40 agonist therapy—particularly when combined with chemotherapy—has demonstrated disease stabilization and improved immune cell infiltration, as observed in early-phase trials using APX005M and selicrelumab." (PMID 40821795, 2025). "For example, in a small cohort of patients with pancreatic ductal adenocarcinoma, tumor regression correlated with TAM infiltration following treatment with chemotherapy and a CD40 agonist." (PMID 38791312, 2024). "Additionally, research has indicated that CD40 agonists can enhance the effectiveness of immune checkpoint inhibitors, such as anti-PD1 and anti-CTLA4, in preclinical models of pancreatic ductal adenocarcinoma (PDAC)." (PMID 40003965, 2025).
asthma (18 papers, 2012 to 2025). "Complementing IL-10 expression in CD40-/- DC10 by IL-10 mRNA transfection fully restored the cells’ abilities to suppress the asthma phenotype." (PMID 33793599, 2021). "DCs present in the BAL of CBD mice displayed an activated phenotype that included upregulation of MHCII and CD40 expression, which is in agreement with DC activation previously observed in asthma models." (PMID 34054347, 2021). "Wild-type DC10 were highly tolerogenic in our mouse model of asthma, while CD40-/- DC10 were somewhat compromised in their regulatory activities." (PMID 33793599, 2021). "In summary, these results indicate that EP4-mediated signaling affect the development of Th2-type asthma and this receptor is the key media in the regulation of CD40-induced IgE production." (PMID 32636842, 2020). "CD40 gene polymorphisms may also influence IgE production in patients with asthma by modulating CD40 expression on B cells." (PMID 33976586, 2021). "These specific genes, whose expression was attenuated by clarithromycin after IL-13 exposure, were dominantly categorized as “extracellular region,” “plasma membrane,” and “defense response” genes, among which asthma-related CD40, NOS2, and CXCL1 were included." (PMID 28219384, 2017). "In asthma, dendritic cells present antigens to CD4 + T cells by expressing MHC class II molecules and rely on co-stimulatory molecules such as CD40, CD80, CD86 to induce T cell activation." (PMID 38664707, 2024). "Significant downregulation of MHCII, CD40 and TNF-α expression in the asthma pathway, blocking acute inflammatory responses such as bronchospasm, edema and airflow obstruction." (PMID 36245510, 2022). "The results showed that pulmonary DCs from OVA-sensitized and -challenged mice treated with MSCs showed reduced expression of CD40, CD80 and CD86 compared with those in the PBS-treated asthma group." (PMID 25936350, 2015). "The increased expression of CD40 ligand that we observed in the asthma group compared with the control group could also relate to the presence of elevated type 1 cytokines since IL-12 has been demonstrated to be produced as a result of enhanced CD40/CD40L interactions." (PMID 23043798, 2012). "As such, we next assessed the regulatory activities of our DC10 in our mouse model of OVA-induced asthma, treating asthmatic mice with OVA-pulsed w.t. or CD40-/- DC10 and assessing their asthma phenotype 4 wk later, when the regulatory effects of DC10 have achieved essentially full penetrance." (PMID 33793599, 2021). "As we known, LPS, as a bacterial product, leads to T-independent (TI) responses, while anti-CD40 mimics CD40 ligand (CD40L, also known as CD154) expressed by antigen-stimulated T cells and reflects the course of asthma characterized by Th2 cell-mediated responses." (PMID 32636842, 2020). "Herein we used wild-type (w.t.)and CD40-/- DC10 to assess the role of CD40 in DC10 reversal of the asthma phenotype in OVA-asthmatic mice, complementing IL-10 expression in the CD40-/- DC to assess whether IL-10 supplementation can over-ride a lack of CD40 signaling in these cells." (PMID 33793599, 2021). "Wild-type DC10 ablated the OVA-asthma phenotype via induction of Foxp3+ Treg responses, but CD40-/- DC10 had no discernible effects on primary facets of the phenotype (e.g., IL-5, IL-9, IL-13 levels, IgE & IgG1 antibodies; p>0.05) and were ≤40% effective in reversal of others." (PMID 33793599, 2021).
diffuse large B-cell lymphoma (17 papers, 2008 to 2024). "Among monoclonal antibodies that have been investigated for their anti-cancer characteristics, the anti-CD40 antibody has been reported to cause apoptosis of diffuse large B-cell lymphoma cell lines with ERK1/2 activation through CD40 signaling." (PMID 27134571, 2016). "Similarly, tumor-associated CD40 expression has a favorable prognostic effect in renal cell carcinoma and diffuse large B-cell lymphoma following chemotherapy." (PMID 32256143, 2020). "Therefore, statistically significant, positive correlations with a signature found in TLR4, TLR9, and CD40 pathway activation were each associated with poor prognosis in diffuse large B cell lymphoma." (PMID 18937865, 2008). "Dacetuzumab is a humanized immunoglobulin G1 mAb against CD40 developed initially for diffuse large B-cell lymphoma (DLBCL)." (PMID 37480137, 2023). "Loss of Mll4 causes a proliferative advantage that expands the germinal centre (GC), which is enhanced by CD40 and IL4 stimulation and represents the cell type that is causative to diffuse large B-cell lymphomas (DLBCL) and follicular lymphomas (FL)." (PMID 32389825, 2020). "For this purpose, we compared RNA-seq data (GSE65422) from non-transformed B cells (resting splenic B cells and germinal center B cells analyzed directly ex vivo; and B cells activated in vitro with a-CD40 and a-IgM antibodies) with B cells resembling diffuse large B cell lymphoma (DLBCL)." (PMID 29312197, 2017). "ChiLob 7/4 is an intermediate CD40 agonist and chimeric IgG1, which was also shown to induce pro-inflammatory cytokines, with promising results in CD40-expressing solid tumors and diffuse large B cell lymphoma resistant to conventional therapy in a phase I clinical trial (NCT01561911)." (PMID 28241846, 2017). "Indeed, monoclonal antibodies targeting CD40 such as Dacetuzumab have been investigated in phase 1 and 2 clinical trials for conditions such as multiple myeloma and diffuse large B cell lymphoma (DLBCL), perhaps paving the way for a new therapeutic for other hematological malignancies such as CLL." (PMID 37064123, 2023). "ChiLob 7/4 is an intermediate CD40 agonist and chimeric IgG1, which was also proved to induce the proinflammatory cytokine and gave promising results in phase 1 clinical studies in CD40-expressing solid tumors and diffuse large B-cell lymphoma resistant to conventional therapy." (PMID 28660349, 2018). "Other phase I and II trials on dacetuzumab in patients with multiple myeloma (MM) and diffuse large B-cell lymphoma (DLBCL), or on ChiLob7/4 (chimeric agonistic CD40 IgG1 mAb) in DLBCL patients have shown a similar safety profile as well as modest clinical activity." (PMID 38440738, 2024). "These included CD40, TRAF1, EBI3, and ICAM1, which were previously established as TES1 target genes in studies of cell lines overexpressing LMP1, including BL-41 Burkitt and BJAB diffuse large B-cell lymphoma models." (PMID 38009935, 2023). "Treatment with dacetuzumab (SGN-40), a humanized IgG1 mAb targeting CD40, did not achieve improved complete remission when combined with rituximab and ifosfamide-carboplatin-etoposide (R-ICE) in relapsed, diffuse, large B-cell lymphoma (DLBCL) in a phase 2 study (NCT00529503)." (PMID 33628584, 2021).
colorectal cancer (16 papers, 2007 to 2026). A primary or metastatic malignant neoplasm that affects the colon or rectum. "Previous research has shown that the expression of the AHRR gene in human colorectal cancer tissue correlates with CD40/CD40L signaling and histological grade." (PMID 40611182, 2025). "This study mainly focused on the tumor infiltrating myeloid cells, and revealed the potential mechanism of immunotherapeutics targeting myeloid cells (anti-CSF1R and anti-CD40 agonism) in mouse models with colorectal cancers." (PMID 36172359, 2022). "We have previously demonstrated that mCD40L causes extensive apoptosis in colorectal carcinoma (CRC) cells that are naturally CD40+ve (HCT116 cells), as well as in CD40−ve cells in which CD40 expression was restored by retroviral transduction (SW480-CD40 cells)." (PMID 36291141, 2022). "Similar anti-tumor activity was observed in a colorectal cancer model (MC38) treated with anti-CD40 and CSF-1R inhibition." (PMID 33804039, 2021). "TRAF3 also plays pro-apoptotic roles in human bladder and colorectal carcinoma cells upon CD40 ligation via BAX/BAK-caspase 9- and ROS- dependent mechanisms." (PMID 34745083, 2021). "In a recent study, the dense infiltration of CD40+ macrophages indicated a favorable prognosis in colorectal cancer patients." (PMID 27119077, 2016). "In the MC38 colorectal cancer model, anti-CD40 therapy alone had minor effects on tumor growth." (PMID 33804039, 2021). "However, one striking observation is that in colorectal carcinoma cells mCD40L-mediated death occurs more rapidly in comparison to other carcinoma cells, leading us to hypothesise that in these cells CD40 ligation may engage a more complex pathway." (PMID 36291141, 2022). "As such, the use of CD40 agonists to expand these activated, cross-presenting DC populations may be warranted as it was reported to result in more effective T cell priming by the DCs in a murine colorectal cancer setting." (PMID 34836966, 2021). "In contrast, colorectal cancer patients rarely had high expression in ICOS and CD40 (RR: 0.30 and 0.40, respectively)." (PMID 37553332, 2023). "The aim of this study was to demonstrate that in vitro activation of the immune checkpoint CD40/CD40L can improve DC action towards bile duct, pancreas, and colorectal carcinoma." (PMID 33180184, 2021). "The CD40 Bs used to generate fusions were derived from a healthy volunteer with neither a family history of hereditary non-polyposis colorectal cancer nor any other known severe disease, in particular no tumor." (PMID 21943054, 2011).
influenza (16 papers, 2009 to 2025). An acute viral infection of the respiratory tract, occurring in isolated cases, in epidemics, or in pandemics; it is caused by serologically different strains of viruses (influenzaviruses) designated A, B, and C, has a 3-day incubation period, and usually lasts for 3 to 10 days. "By day 7, expression of Ccl3, Cxcl9, Cd86, Il-6, Cd80, and Cxcl11 remained elevated in young adult lung in response to H1N1, while expression of Ccl5, Ccl4, and Cd40 remained elevated in response to either strain of influenza." (PMID 34829979, 2021). "Culturing B cells in the presence of anti-CD40, IL-4 and IL-21 was found to trigger influenza antigen-specific ASC in frequencies similar to R848 and IL-2 stimulation." (PMID 32069813, 2020). "Herein, we report that the combination of agonistic anti-CD40, IL-4 and IL-21 affords polyclonal B cell stimulation that was comparable to R848 and IL-2 for detection of influenza-specific memory B cells." (PMID 32069813, 2020). "CD40 is also involved in the self-help feedback loop of influenza-specific CD4+ T cells, in which previously primed CD4+ T cells license DCs to better prime the next generation of CD4+ T cells." (PMID 26910342, 2016). "In the context of influenza infection, the co-stimulatory molecule CD40 has a role in helping both the CD4+ and CD8+ T cell responses." (PMID 26910342, 2016). "Patients infected with gram-negative bacteria or EBV showed a marked increase in monocyte CD40, while this effect was less pronounced for tuberculosis, borrelia and influenza." (PMID 20626864, 2010). "In addition, after stimulating CD4+CXCR5+Tfh cells with an influenza antigen, it was found that the level of CD40 L in the OS group was significantly reduced and the level of IFNγ was increased considerably." (PMID 35494526, 2022). "The immunogenicity observed in the hu-mice model are consistent with those of our previous CD40-targeted influenza and HIV vaccine studies and demonstrate that αCD40.RBD could be a potent prime or boost vaccine for eliciting RBD-specific T- and B-cell responses." (PMID 34471122, 2021). "For example, mice lacking CD40 or CD4+ T cells resulted in detectable levels of influenza-specific IgG after influenza virus infection, providing a similar level of protection against influenza virus re-infection comparable to that of WT mice." (PMID 39772016, 2024). "CD40 has previously been shown to regulate immune response and promotes protection against the virus while PARP1 has been highlighted as a host factor that can regulate the polymerase activity of influenza." (PMID 31787983, 2019). "On PSLB, CD40L localizes to the center of the IS predominantly in the presence of CD40 and HLA-DRB1*09:01-influenza HA338-355, not in the presence of HLA-DRB1*09:01:CLIP." (PMID 31469364, 2019). "Also NK cells provide valuable information since a marked increase was evident only in the influenza group (but not in the case of EBV, despite a clear virus pattern as determined by monocyte CD40 plus CD8+ T cells)." (PMID 20626864, 2010). "Interestingly, other researchers have shown that innate inflammation in the setting of influenza challenge was independent of TNF signaling and CD40 signaling, whereas we found that TNFR and CD40 played a critical role in autoreactive memory T cell–induced innate inflammation and pathology." (PMID 40279312, 2025).